SIRT6 (sirtuin 6)
Diseases named in the same sentence as SIRT6 in open-access papers (continued):
Sharing a sentence is not in itself a finding about the gene and the disease.
Insulin resistance (43 papers, 2012 to 2026). Increased resistance towards insulin, that is, diminished effectiveness of insulin in reducing blood glucose levels. "The beneficial effects of USP10 on insulin sensitivity were abolished by Sirt6 deficiency, and overexpression of Sirt6 strongly abrogated the insulin resistance observed in Usp10KO mice." (PMID 36834633, 2023). "Myeloid Sirt6 deficiency causes insulin resistance in HFD–fed mice by eliciting macrophage polarization toward an M1 phenotype, and facilitates the development of HFD-induced atherosclerosis." (PMID 30574122, 2018). "Furthermore, ubiquitin-specific peptidase 10 (USP10) interacts with SIRT6 and inhibits its ubiquitination and degradation, while Sirt6 overexpression attenuates USP10 deficiency-potentiated hepatic insulin resistance, steatosis, and inflammation." (PMID 39372420, 2024). "Zhang and colleagues reported that physical exercise intervention ameliorates insulin resistance and improves SIRT6-mediated insulin signaling transduction in the liver of obese rats." (PMID 39372420, 2024). "In contrast, fat-specific and muscle-specific Sirt6 KO mice exhibit insulin resistance and glucose intolerance." (PMID 38201252, 2023). "Consistently, adipocyte-specific Sirt6 KO mice exhibit increased insulin resistance and inflammation in the adipose tissue." (PMID 38201252, 2023). "After a high-fat diet, liver-specific SIRT6 knockout mice have increased glycolysis, de novo lipogenesis, and β-oxidation, which aggravate fatty liver and insulin resistance." (PMID 37298491, 2023). "Adipocyte-specific Sirt6 ko mice gain more body weight and fat mass than wild-type mice and show glucose intolerance and insulin resistance, with decreased M2 macrophages in the adipose tissue." (PMID 38016059, 2023). "Another study claimed that Sirt6 activation protects against insulin resistance in neonatal rat cardiomyocytes in H9C2 cell line." (PMID 37497437, 2023). "While genetic, chronic SIRT6 inhibition in macrophages promotes inflammation and insulin resistance, pharmacological inhibition of SIRT6 ameliorates glucose intolerance during diet-induced obesity (DIO)." (PMID 35150745, 2022). "Strong scientific evidence supports SIRT6 activity in insulin resistance, SIRT3 activity in protecting against age-related cardiac hypertrophy, and NAD+ levels in angiogenesis and blood flow." (PMID 36361416, 2022). "Decreased SIRT6 protein levels in the liver of obese mice and NAFLD patients, and fat-specific SIRT6 deficiency, increased inflammation and insulin resistance induced by HFD in mice." (PMID 36008973, 2022). "In obese rats, exercise improves SIRT6-mediated insulin signaling and ameliorates insulin resistance." (PMID 33806509, 2021). "It has been demonstrated that USP10 inhibits hepatic steatosis and insulin resistance via Sirt6, in which Sirt6 represses the transcription levels of SREBP1/SREBP2 and their target genes." (PMID 33622377, 2021). "SIRT6 overexpression markedly ameliorated the effects of USP10 deficiency on hepatic steatosis, insulin resistance, and inflammation." (PMID 33133065, 2020). "In this study, we observed that Sirt6 deficiency in adipocytes of lean mice is sufficient to cause proinflammatory macrophage accumulation in WAT, cytokine production, and systemic insulin resistance under NCD, similar to that observed in obese mice." (PMID 31113929, 2019). "Third, Sirt6 deficiency resulted in impaired insulin signaling and increased apoptosis under ER stress, whereas Sirt6 overexpression and Sirt6 activation improved hepatic insulin resistance and apoptosis." (PMID 31541078, 2019). "Overall, results of this study provide a clinical evidence of the role of SIRT6 role in pre-DM insulin resistance and inflammation in the adipose tissue of obese patients." (PMID 30845774, 2019).
Insulin resistance (continued). "The animal study demonstrated that Sirt6 deficiency in adipocytes leads to increased accumulation of macrophages in WAT and systemic insulin resistance under NCD, which recapitulates the phenotypes observed in HFD-fed or genetically obese mice." (PMID 31113929, 2019). "In adipose tissue, Sirt6 deficiency increases macrophage infiltration and adipose tissue inflammation and promotes HFD-induced insulin resistance." (PMID 29535637, 2018). "It's worth noting that SIRT1, SIRT2, SIRT3, and SIRT6 are positive regulators of insulin resistance in most cases." (PMID 30559718, 2018). "USP10 inhibits hepatic steatosis, insulin resistance, and inflammation through Sirt6." (PMID 39430239, 2024). "However, Sirt6-KO mice showed insulin resistance, which corresponded with decreased expression of adiponectin in white adipose tissue (WAT) and UCP1 in BAT and increased inflammatory signaling in both WAT and BAT." (PMID 36465178, 2022). "Sirtuins appear to have a complex but generally protective effect against obesity; increasing NAD+ levels or SIRT1 and SIRT6 activity may be a helpful therapeutic strategy for preventing and treating type 2 diabetes, MetS, and insulin resistance." (PMID 36361416, 2022). "It is through this process that myeloid Sirt6 may counteract metabolic dysregulation and insulin resistance." (PMID 34125994, 2021). "The data described in this review reveal SIRT1 and SIRT6 as multifaceted mediators of energy metabolism, affecting processes such as food intake, food preference, puberty, body weight, adiposity, glucose homeostasis and insulin resistance." (PMID 33572672, 2021). "However, further investigation into the targets and functions of SIRT1, SIRT2, SIRT3, and SIRT6 will aid in the development of new strategies to treat insulin resistance and T2DM." (PMID 30972029, 2019). "This study was designed to address the hypothesis that Sirt6 ameliorates hepatic ER stress by deacetylating XBP1s to improve fat accumulation, apoptosis, and insulin resistance in hepatocytes." (PMID 31541078, 2019). "Our results indicate a reduction in Sirt6 expression in NAFLD and other conditions associated with ER stress, and the consequent increase in XBP1s activity via acetylation-dependent protein stabilization leads to enhanced steatosis, insulin resistance, and injury in the liver." (PMID 31541078, 2019). "Thus, SIRT6 may have beneficial effects on glucose metabolism, including insulin resistance and T2DM, by reducing inflammation and improving mitochondrial function." (PMID 30972029, 2019). "Upregulated Sirt6 expression inhibited HFD-induced hepatic steatosis, insulin resistance, and inflammation." (PMID 38136219, 2023). "Both SIRT6 and SIRT7 can participate in liver lipid metabolism, endoplasmic reticulum stress, and insulin resistance, and regulate the progression of NAFLD." (PMID 36008973, 2022). "SIRT6 overexpression can improve hepatic steatosis, insulin resistance, and inflammation, which regulates hepatic steatosis by interacting with USP10 and inhibiting SIRT6 ubiquitin and degradation." (PMID 36008973, 2022). "It potentially alleviates inflammation and insulin resistance in skeletal muscle and adipose tissues through GPR35/AMPK and SIRT6-mediated pathways." (PMID 35282457, 2022). "Another ongoing research in this area involves sirtuin proteins, particularly sirtuin-6 (SIRT6), which is believed to have a potential therapeutic effect on insulin resistance." (PMID 34909309, 2021). "A compound, kynurenic acid, was found to reduce insulin resistance, while palmitate induced inflammation in adipocytes by increasing fatty acid oxidation through AMPK and SIRT6 in mice." (PMID 33806509, 2021). "Tm-induced apoptosis and insulin resistance, which were assessed by western blotting for pro-apoptotic molecules or Akt phosphorylation and TUNEL staining, were more evident in Sirt6 KO livers than in WT livers." (PMID 31541078, 2019).
Insulin resistance (continued). "Sirt6 deletion increases inflammation in the mice adipose tissue and promotes HFD-induced insulin resistance." (PMID 30574122, 2018). "The increase in KYNA reduced palmitate-induced inflammation and insulin resistance in adipose tissue and skeletal muscle of HFD mice via the G protein–coupled receptor 35 (Gpr35)/AMP-activated protein kinase (AMPK) and elevated sirtuin 6 (SIRT6) pathways." (PMID 40522819, 2025). "In vitro evidence on the endothelial cell models of insulin resistance and hyperglycemia showed the ability of Magliocco to reduce reactive oxygen species (ROS) (p < 0.01) and cytokine release (p < 0.01) and to upregulate SIRT1 and SIRT6 (p < 0.01)." (PMID 34073604, 2021). "In addition, we observed a marked decrease in Sirt6 expression in eWAT from 16-week HFD-fed mice compared with NCD-fed mice, suggesting a possible contribution of adipose Sirt6 to weight gain and/or insulin resistance." (PMID 31113929, 2019). "Interestingly, deletion of adipocyte Sirt6 accelerates M1 macrophage infiltration into WAT with no change in the M2 macrophage population and promotes systemic insulin resistance in mice fed a HFD19." (PMID 31113929, 2019). "Overexpression of SIRT6 in mice provides protection against metabolic pathologies from diet-induced changes, but SIRT6 knockout mice have increased glucose transport and decreased levels of TNF-alpha in the serum which has a negative effect on insulin resistance." (PMID 36225477, 2022).
colon carcinoma (39 papers, 2018 to 2026). "SIRT6 is pathologically downregulated in colon cancer and its low expression is associated with a poor prognosis and more aggressive progression of this disease." (PMID 35326523, 2022). "A recent study showed that high levels of SIRT6 expression in colon cancer are associated with a better prognosis." (PMID 33800266, 2021). "In colon cancer, decreased expression of Nu-SIRT6 was associated with more frequent relapse in the subpopulation of patients with lymph node metastasis or higher levels of C-reactive protein." (PMID 30524965, 2018). "Consistent with our results, immunohistochemical expression of SIRT6 was higher in colon cancer tissue than adjacent normal tissue, and was associated with higher T stage, presence of lymph node metastasis, and higher histologic grade of colon cancers." (PMID 30524965, 2018). "Moreover, Lower SIRT6 levels were demonstrated in colon cancer and were associated with shorter survival than those of patients with higher SIRT6 expression." (PMID 35172823, 2022). "This role is particularly evident in pathological contexts; for instance, in colon cancer cells stimulated by palmitic acid, PKCζ directly phosphorylates sirtuin 6 (SIRT6) at Thr‐294." (PMID 41244006, 2025). "We compared SIRT6 expression in two isogenic colon carcinoma cell lines with varying anoikis potential: SW480 cells and SW620 cells." (PMID 38891773, 2024). "It is also verified that miR-34c-5p stimulated cellular proliferation by regulating the SIRT6-mediated activation of the JAK2/STAT3 signaling pathway in colon cancer cells." (PMID 38185635, 2024). "Oleanolic acid induces both apoptosis and pro-survival mitophagy via the p38/forkhead box O3a (FOXO3a)/Sirt6 signaling in colon cancer cells, and also increases the chemosensitivity of colon cancer cells to 5-Fu." (PMID 38102686, 2023). "Quercetin arrested colon cancer cell growth by modulating expression of aging proteins including Sirtuin-6 and Klotho and also by inhibiting telomerase activity to restrict the telomere length which is evident from qPCR analysis." (PMID 36807774, 2023). "On the other hand, SIRT6 also serves as a negative regulator of lipid metabolism, with the EGF-dependent down-regulation of SIRT6 (FOXO3/SIRT6) resulting in enhanced LD biogenesis in human colon cancer cells." (PMID 37371492, 2023). "It was shown that dysregulated USP10 function promotes carcinogenesis via SIRT6 degradation in human colon cancer and the crosstalk between UPS10 and SIRT6 controls cell-cycle progression and proliferation." (PMID 38203666, 2023). "Further, quercetin also modulates the expression of anti-aging genes SIRT-6 and Klotho to inhibit colon cancer cell proliferation." (PMID 36807774, 2023). "Our findings connected SIRT6, histone crotonylation, DNA damage, and colon cancer, providing potential novel therapeutic targets." (PMID 35936700, 2022). "SIRT6 was proposed to serve as a prognostic indicator and potential therapeutic target in colon cancer." (PMID 35326523, 2022). "In colon cancer, SIRT6 deacetylates H3K9ac to promote the EMT process by reading snail and inhibiting TET1 transcription, further promoting tumorigenesis." (PMID 35463332, 2022). "Recent evidence shows that SIRT6 exerts a tumor-suppressive effect by inhibiting the proliferation and promoting the apoptosis of various cancer cells, such as colon cancer, pancreatic cancer and glioma cells." (PMID 35915188, 2022). "The apoptosis levels of SW620 colon cancer cells overexpressing SIRT6 increased, and their proliferation ability was weakened." (PMID 35463332, 2022). "Our previous study revealed that, AKT/FoxO3a pathway regulates SIRT6 expression in colon cancer and inhibition of AKT triggers SIRT6 transcription via FoxO3a activation, which significantly promotes cell death." (PMID 35715817, 2022). "We discovered that genes with promoter occupied by histone crotonylation were enriched in colon cancer patients with a low activity of SIRT6." (PMID 35936700, 2022).
colon carcinoma (continued). "In an independent soft agar assay using HCT116 colon cancer cells, SIRT6 KO cells exhibited significantly increased anchorage independent colony formation (32% increase, p < 0.01), a hallmark of cancer cell malignancy." (PMID 34573442, 2021). "In line with this, USP10 expression correlates positively with SIRT6 expression and both proteins are downregulated in colon cancer." (PMID 33800266, 2021). "Tian and Yuan reported that overexpression of SIRT6 inhibited migration and invasion in colon cancer cells in vitro." (PMID 33335996, 2020). "It has also been reported that SIRT6 cooperated with special small molecules is deleted or reduced in 20% of all cancers, such as colon cancers and rectal adenocarcinoma, according to the Cancer Genome Atlas database." (PMID 32283646, 2020). "On the other hand, downregulation of SIRT6 expression in colon cancer tissues negatively correlated with the overall survival of colon cancer patients." (PMID 32488123, 2020). "The molecular mechanism through which δVB triggers colon cancer cell autophagy and apoptosis involves altered cellular redox homeostasis and sirtuin 6 (SIRT6) modulation." (PMID 32878301, 2020). "In order to see a big picture, it would be important to screen compounds effect on SIRT6 in a panel of several colon cancer cell lines." (PMID 32905943, 2020). "Additionally, TFAM promotes the growth and metastasis of colon cancer in vitro and in vivo, while SIRT6 was inhibited." (PMID 41362737, 2026). "It is assumed that the miR-34c-5p/SIRT6/JAK2/STAT3 axis could be an innovative therapeutic target that opens new insights into developing treatment approaches for colon cancer therapy." (PMID 38185635, 2024). "Therefore, our data comprehend that SIRT-6 activation was required for apoptosis to occur in colon cancer cell lines." (PMID 36807774, 2023). "However, studies have shown that the expression of SIRT6 protein in colon cancer tissues is downregulated, and patients with higher SIRT6 expression show better prognosis." (PMID 35463332, 2022). "The level of H3K27cr was reduced during DNA damage in colon cancer, which might be mediated by SIRT6." (PMID 35936700, 2022). "Indeed, following the action of the non-coding RNA miRNA-34c-5p, JAK2/STAT3 pathway is activated, thereby negatively regulating SIRT6, inhibiting apoptosis, and inducing colon cancer growth." (PMID 33800266, 2021). "Also, SIRT6 retarded the malignant progression of colon cancer via mediating PTEN/AKT signaling, and SIRT6 has been reported to be a tumor-suppressive gene in other types of human cancer." (PMID 33510943, 2021). "Moreover, SIRT6 downregulation in colon cancer tissues and different colon cancer cell lines negatively correlated with the overall survival of patients through the regulation of PTEN/AKT signaling pathway." (PMID 32488123, 2020). "Among dietary regulators of cellular redox homeostasis, δVB has been recently shown to induce a ROS-mediated apoptotic cell death in human colon cancer LoVo cells via SIRT6 activation and changes in mitochondrial integrity initiated by excessive ROS accumulation." (PMID 32878301, 2020). "Furthermore, downregulated SIRT-6 expression has been identified in the early stages of human colon cancer and is maintained during tumor growth, suggesting that a low level of SIRT-6 may have been involved in the initiation and progression of colon cancer." (PMID 36807774, 2023). "In addition to the regulation of aging-associated miRNA and anti-aging protein activity such as Klotho and SIRT-6, inhibition of telomerase activity leading to the shortening of telomere length paved an interesting avenue towards future designing of colon cancer therapeutics." (PMID 36807774, 2023).
colon carcinoma (continued). "Moreover, USP10 could inhibit c-Myc transcriptional activation via stabilization of SIRT6 to inhibit tumor formation in colon cancer." (PMID 35277183, 2022). "For example, in colon cancer, USP10 interacted with and stabilized SIRT6 through inhibiting SIRT6’s ubiquitination, suppressing proliferation." (PMID 35627217, 2022). "For example, in colon cancer, USP10 interacted with and stabilized SIRT6 through suppressing SIRT6 ubiquitination." (PMID 35627217, 2022). "Sirtuin 6 (SIRT6) was recently reported to interact with PTEN, resulting in higher protein expression levels and lipid phosphatase activity in colon cancer cells." (PMID 33659963, 2020). "Sirtuin 6 (SIRT6) is an NAD+-dependent deacetylase with a significant role in 20% of all cancers, such as colon cancers and rectal adenocarcinoma." (PMID 32283646, 2020). "Among SIRT6 interactors, Snail represents a point of connection between SIRT6 and EMT in colon carcinoma cells, although the deacetylation site on Snail protein is unknown." (PMID 35745656, 2022). "SIRT6 can not only upregulate the expression of tumor suppressors phosphatase and tensin (PTEN), and phosphatidylinositol-4,5-biphosphate (PIP2), but also can downregulate AKT1, mTOR, cyclin D1, and c-myc to inhibit the progression of colon cancer." (PMID 35172823, 2022). "Researches reveal that SIRT6 is overexpressed in osteosarcoma, papillary thyroid cancer (PTC), prostate cancer, conversely reduced in renal cell carcinoma (RCC), pancreatic ductal adenocarcinoma (PDAC), colon cancer (CRC), non-small cell lung cancer (NSCLC)." (PMID 35172823, 2022). "Besides, the H3K9 deacetylase activity of SIRT6 mediates EMT and metastasis in malignant human colon carcinoma." (PMID 31485224, 2019). "In colon cancer cells, ROS production induced by milk betaines was not a secondary effect but it triggered SIRT6 modulation and cell death, as demonstrated by reduced SIRT6 expression and pro-cell death effects when ROS generation was suppressed by the antioxidant N-acetyl-L-cysteine." (PMID 32878301, 2020).